KDM4A (lysine demethylase 4A)
Diseases named in the same sentence as KDM4A in open-access papers (continued):
Sharing a sentence is not in itself a finding about the gene and the disease.
cancer (85 papers, 2011 to 2026). A tumor composed of atypical neoplastic, often pleomorphic cells that invade other tissues. "KDM4A isoform plays an important role in the epigenetic dysregulation in various cancers and is linked to aggressive disease and poor clinical outcomes." (PMID 38129913, 2023). "These family members are involved in diverse biological pathways linked to cancer such as Akt-mTOR signaling for KDM4A, Wnt signaling for KDM4B, targeting pluripotency factors for KDM4C, and hypoxia-inducible factor 1 signaling for KDM4D." (PMID 36975603, 2023). "Dysregulation of KDM4A expression has been linked to various human cancers, including breast, colon, gastric, prostate, and non-small cell lung cancers." (PMID 37553362, 2023). "Several KDMs (2B, 4A, 4C, 6A, 8) were shown to be associated with the capacity for SCC cancer cell invasion, and the knockdown of KDM4A reduced lymph node metastasis in an orthotopic mouse model of SCC of the floor of the mouth." (PMID 35326475, 2022). "The overexpression of KDM4A is known to be associated with cell proliferation and poor prognosis in several cancers." (PMID 29682202, 2018). "KDM4A has been described as over-expressed in a range of cancer types although the underlying mechanism is unclear." (PMID 28894274, 2017). "To evaluate KDM4A as a potential therapeutic target we examined the KDM4A-dependent contribution to key biological processes associated with cancer aggressiveness." (PMID 28894274, 2017). "Notably, mutations in Kdm4a exhibit the most pronounced inhibitory effects on the growth of cancer organoids among them." (PMID 39461328, 2024). "Accumulating evidence suggests that KDM4A is not only involved in body homeostasis (such as cell proliferation, migration and differentiation, and tissue development) but also associated with multiple human diseases, especially cancers." (PMID 37692513, 2023). "The KDM4A cluster has 32 regulated genes associated with rs135786834; KDM4A encodes a histone lysine demethylase able to modify trimethylated H3-K9/K36 to dimethylated products, contributing to gene expression, cellular differentiation and cancer development." (PMID 32000679, 2020). "Recently, KDM4A was shown to be implicated in pathological states such as cancer." (PMID 32523934, 2020). "In keeping with a role for KDM4A activity in controlling DNA replication, overexpression of KDM4A leads to genomic instability in a demethylase‐dependent manner, through driving re‐replication and site‐specific copy gain in genomic regions implicated in cancer." (PMID 26564907, 2015). "KDM4A overexpression in cancer is driving the development of therapeutic inhibitors that are designed to target its transcriptional functions." (PMID 41168084, 2026). "KDM4-A/B/C, preferentially demethylating di- and tri-methylated lysine 9 on histone H3, are overexpressed in cancers and considered interesting therapeutic targets." (PMID 40537846, 2025). "Knockdown of KDM4A (KD-KDM4A) in cellular models has been shown to reduce cell proliferation, making it a subject of interest in various cancers." (PMID 41244052, 2025). "By controlling cell proliferation, cell death, DNA repair, and self-renewal, K36 demethylase 4A (KDM4A) demethylates specific histone H3 lysine, which indirectly influences cell division and contributes to the development of cancer." (PMID 40227645, 2025). "In MCF7 and HCT116 cancer cells, the CRISPRoff + sgRNA-KDM4A complex completely blocked KDM4A gene upregulation induced by QC6352, although no further repression was achieved." (PMID 40537846, 2025). "The results provide a mechanisticclue into KDM4A’s role in cancers that rely on heightened ribosomalactivity to support uncontrolled cellular proliferation." (PMID 39808475, 2025). "We choose to target members of the histone-lysine demethylase KDM4 family as models, as these are seen as promising therapeutic targets and KDM4A-targeting epi-drugs are in development, mainly against cancer." (PMID 40537846, 2025).
cancer (continued). "Through drug screening in tumor organoids, we identified that ML324, a histone lysine demethylase 4A (KDM4A) inhibitor, exhibits potent antitumor effects in both in vitro and in vivo cancer models." (PMID 39461328, 2024). "In TCGA pan‐cancer database, tumour tissues generally exhibited higher expression levels of KDM4A, KDM4B and KDM4D compared to normal tissues." (PMID 38390756, 2024). "Further exploration of the biological functions of KDM4A in cancer and adaptation profiles of KDM4A inhibitors will advance the applications of KDM4A inhibitors for clinical use in the future." (PMID 37692513, 2023). "Second, because of the heterogeneity of KDM4A-mediated cancers, it is imperative to identify the anticancer profile of KDM4A inhibitors to progress them into clinical use for precision treatment." (PMID 37692513, 2023). "KDM4A is also aberrantly expressed in multiple cancers and contributes to tumorigenesis and drug resistance by transcriptionally modulating different effector proteins." (PMID 37692513, 2023). "In HER2 breast leptomeningeal carcinomatosis (HER2 LC), KDM4A promotes cancer growth by increasing GMCSF levels." (PMID 37692513, 2023). "Although there are many reports on the roles of KDM4A in cancer progression and development, more studies are still necessary to explore the precise functions of KDM4A in a variety of cancers due to their heterogeneity." (PMID 37692513, 2023). "In summary, KDM4A inhibition is an effective strategy to treat multiple KDM4A-overexpressing cancers and combat many KDM4A-induced drug-resistant cancers." (PMID 37692513, 2023). "KDM4A is also amplified in other cancers and promotes their progression via a variety of mechanisms." (PMID 37692513, 2023). "KDM4A is either deleted or overexpressed (predominantly through gene amplification) in several types of cancer including lung, breast, ovarian, and head and neck cancer." (PMID 35661267, 2022). "Increased expression of KDM4A has been documented in various types of cancers, and KDM4A serves as an oncogene in CC." (PMID 35287356, 2022). "Analysis of ENCORI pan cancer co-expression demonstrated a positive correlation between KDM4A mRNA and HIF1α mRNA level in CC tissues." (PMID 35287356, 2022). "The inhibition of KDM4A reduced the number of cancer stem cells and inhibited tumorsphere formation in SCC cells." (PMID 35326475, 2022). "SETD2’s function can also be affected in cancer through misregulated expression of the demethylase KDM4A, which demethylates both H3K36me3 and H3K9me3." (PMID 35661267, 2022). "Similar activities have been found in other cancers and KDM4A inhibitors were shown to regulate growth through induction of apoptosis and inhibition of cell cycle progression." (PMID 35069219, 2021). "Accumulating evidence shows that the epigenetic regulatory protein KDM4A plays an important role in cancer and the potential for targeting KDM4A for cancer therapy exists." (PMID 34111227, 2021). "Bioinformatic analysis revealed that 14 of the 44 (32%) potential KDM4A-KIKAT/LINC01061 target genes were found in the cancer-related pathways identified in KIKAT/LINC01061-overexpressing SLK cells, and AMOT was one of them." (PMID 34111227, 2021). "KDM4A is the first identified histone trimethyl demethylase that has been demonstrated as an oncogene in various cancers." (PMID 34111227, 2021). "KDM4A is a histone lysine demethylase that has been described as an oncogene in various types of cancer." (PMID 34111227, 2021).
cancer (continued). "Some small molecule inhibitors can also suppress cancer growth and it indicates that the functions of KDM4A are depended on its catalytic activity." (PMID 29651880, 2018). "KDM4A is abnormally expressed in cancer, affecting the expression of multiple targets, such as the CHD5 gene." (PMID 29682202, 2018). "KDM4A has been shown to play an important role in gene expression, cellular differentiation and cancer." (PMID 29299176, 2017). "KDM4A expression has been reported to be increased in several cancer types including colorectal, this combined with a number of functional studies have suggested KDM4A is an attractive target for cancer therapy." (PMID 28894274, 2017). "Amplification of KDM4A gene copy number, or of its mRNA expression, has been observed in various cancers." (PMID 27624942, 2016). "Cancer cells frequently harbour centrosome abnormalities and may alter KDM4A expression to compensate for this stress." (PMID 41168084, 2026). "KDM4A inhibition could exploit this dependency, selectively forcing cancer cells with centrosome defects into potentially lethal multipolar divisions, while normal cells with intact centrosome control mechanisms would remain unaffected." (PMID 41168084, 2026). "Unlike HEK293T cells, where the downregulation of KDM4A did not impact cell growth, both HCT116 and MCF7 cancer cells exhibited reduced cell proliferation following the decrease in KDM4A gene expression induced by CRISPRoff plus sgRNA-KDM4A compared to the controls." (PMID 40537846, 2025). "Given that KDM4A is overexpressedin multiple cancers, it is reasonable to speculate that KDM4A-mediatedprotein upregulation plays a critical role in tumorigenesis, whichrequires heightened ribosomal activity to support uncontrolled cellularproliferation." (PMID 39808475, 2025). "Given the crucial roles of KDM4A in tumorigenesis and drug resistance, many pharmacologists and pharmaceutical chemists have been devoted to discovering and developing KDM4A inhibitors to combat KDM4A-mediated cancers." (PMID 37692513, 2023). "Then, the role of KDM4A in the tumorigenesis of various cancers is summarized in detail." (PMID 37692513, 2023). "Knockout of KDM4A from K-Ras-activated A549 cells triggers the senescence of cancer cells." (PMID 37692513, 2023). "In addition, KDM4A has been found to regulate other cancer-related genes (CXCL5, ADAM12, and JAG1) by removing methyl groups from H3K9me3 in A549 cells." (PMID 37692513, 2023). "In addition, the classification of KDM4A inhibitors and their therapeutic mechanisms for cancer, as well as the current challenges and potential opportunities of KDM4A for anticancer therapy, are discussed." (PMID 37692513, 2023). "Interestingly, although compounds 35–39 exhibited improved in vitro KDM4A-inhibitory activity against compound 34, compound 34 had the best anti-proliferative activity against different cancer cells." (PMID 37692513, 2023). "Our study warrants further investigation into the molecular mechanism of translation regulation by SETD2, as well as studies to determine whether this function contributes to tumor development in SETD2 mutant or KDM4A-overexpressing cancers." (PMID 36052643, 2022). "In addition to the viral effect, KDM4A has also been recognized as an oncogene that is highly expressed in various human cancers and inhibits apoptosis (42, –, 44)." (PMID 35914074, 2022). "Together, our results demonstrated a novel mechanism for KIKAT/LINC01061-mediated epigenetic regulation of KDM4A and their interaction may serve as a potential target for cancer therapy." (PMID 34111227, 2021). "Our data reveal a novel lncRNA-mediated regulation of the epigenetic function of KDM4A and demonstrate this lncRNA-chromatin modifier interaction may serve as a potential target in cancer therapy." (PMID 34111227, 2021). "KDM4A is known to play a role in several cellular physiological processes, and was recently found overexpressed in a number of pathological states, including cancer." (PMID 32523934, 2020).
cancer (continued). "Together these results indicate that fisetin inhibits cancer-cell proliferation by inducing DNA damage via RFXAP/KDM4A-dependent demethylation of histone H3K36, which might be a novel therapeutic target for PDAC." (PMID 33093461, 2020). "Clinically used iron chelator deferasirox was shown to potently inhibit KDM4A in vitro, and some of its derivatives with improved cell permeability were shown to significantly upregulate histone trimethylation and act as potent cancer cell growth inhibitors." (PMID 32523934, 2020). "Notably, the cellular localization and distribution patterns of KDM4A protein were highly consistent with that of RFX5 protein in the continuous sections of the same cancer nest." (PMID 32883983, 2020). "Therefore, efforts to develop new inhibitors able to block KDM4A activity and inhibit cancer cell proliferation are increasing." (PMID 32523934, 2020). "Clinical studies found that the demethylases of H3K9me2 and me3, such as lysine (K)-specific demethylase 3A (KDM3A, also known as JMJD1A or JHDM2A) and lysine (K)-specific demethylase 4A/B/C (KDM4A/B/C), are highly expressed in cancer tissues and regulate tumorigenesis." (PMID 30867030, 2019). "The overexpression of KDM4A also plays significant roles in some other types of cancers." (PMID 29651880, 2018). "Identifying how KDM4A inhibits gene expression has a therapeutic impact on cancer in the future; therefore, understanding the molecular mechanisms underlying the effects of KDM4A and their implications in cancer are an important topic for future clinical research." (PMID 29682202, 2018). "Finally, we show that the JmjN peptide has the ability to abolish KDM4A/C dimerization and consequent demethylase activity, thus highlighting its possible application as a new cancer chemotherapeutic agent." (PMID 29682190, 2018). "Thus, the KDM4 dimer-interactome emerging from the present study bears potential implications for cancer therapeutics via selective inhibition of KDM4A/C demethylase activity using JmjN-based peptidomimetics." (PMID 29682190, 2018). "Addition of KDM4A expression improved the discriminatory accuracy of standard clinicopathologic features for prediction of cancer-specific survival (Model 4, area under the curve = 0.740, 95% confidence interval = 0.685 to 0.795, and Model 3, AUC = 0.695, 95% CI = 0.637 to 0.753, respectively)." (PMID 29113308, 2017). "Since KDM4A plays a role in cancer development, FBXO22 seems to be a tumor suppressor." (PMID 29299176, 2017). "Here we report that histone demethylase KDM4A/JMJD2A, which is involved in the regulation of cell proliferation and is overexpressed in some cancers, interacts with RNA Polymerase I, associates with active ribosomal RNA genes and is required for serum-induced activation of rDNA transcription." (PMID 26729372, 2016). "In addition, FRA1 is transcriptionally induced by a number of cancer relevant transcription factors including c-Jun, c-Fos and c-Myc, and epigenetic modulators such as histone demethylase KDM4A." (PMID 27144339, 2016). "Our own results suggest that decreased KDM4A expression could contribute to mTOR activation during cancer development, suggesting that this demethylase could act as a context-dependent oncogene." (PMID 27624942, 2016). "NCOA2, KDM1A, KDM4A, KDM5B and MED1 are AR coregulators implicated in prostate and other cancers." (PMID 26461474, 2015). "Based on our findings in primary and cancer cells, we hypothesized that hypoxia-induced KDM4A stabilization and copy gains were evolutionarily conserved responses." (PMID 25995187, 2015). "Among the most important histone demethylases associated with the development of cancer are LSD-1/KDM1A, and members of the Jumonji family JARID1A-1C/KDM5A-5C, JHDM1B/KDM2B, JMJD2C/KDM4C, JMJD2A/KDM4A, JMJD3/KDM6B, and UTX/KDM6A, which will be analyzed in detail in the following paragraphs." (PMID 24280700, 2012).
cancer (continued). "Lysine (K)-specific demethylase 4A (KDM4A/JMJD2A) is a member of the Jumonji domain 2 histone demethylases family that catalyses histone demethylation from lysine residues, transcriptionally regulates gene expressions in tumor cells, and serves as a potential therapeutic target for cancers." (PMID 35287356, 2022). "Indeed, the over-expression of KDM4A promotes transcription in some types of cancers." (PMID 35326475, 2022). "Interestingly, our data also implicate KDM4A in the suppression of HLA expression, which is reminiscent of the loss of heterozygocity in MPM specimen with high tumor burden, further supporting immune evasion mechanisms of the cancer cells." (PMID 35069219, 2021). "For instance, ER+ BCs exhibit overexpression of KDM4A and KDM4B; the two enzymes promote cancer growth and metastasis by targeting either the Notch1-NICD-dependent signaling (for KDM4A) or the estrogen signaling (for KDM4B) pathways." (PMID 40141248, 2025). "KDM4A ablation, especially when synergized with PD1 blockade therapy, was demonstrated to effectively inhibit SCC growth and metastasis and eradicate cancer stem cells." (PMID 39519018, 2024). "In this type of cancer, the lncRNA KIKAT/LINC01061 has been identified as a binding partner of KDM4A, a histone lysine trimethyl demethylase known as an oncogene in various cancer types." (PMID 38918813, 2024). "RAS-association domain family 1 A (RASSF1A) is a kind of RAS effector that regulates cell proliferation and apoptosis, and KDM4A reduces the transcription of RASSF1A by reducing the occurrence of H3K9me2/3 on its promoter and thus promoting cancer progression." (PMID 37692513, 2023). "Therefore, KDM4A may represent a suitable therapeutic target for cancer treatment." (PMID 38129913, 2023). "KDM4A, a member of the JMJD2 family, is dysregulated in several cancer types and plays an important role in proliferation, invasion, and metastasis through complex mechanisms." (PMID 37553362, 2023). "Accumulating evidence supports the oncogenic potential of KDM4A, KDM4B, and KDM4C, which are overexpressed in several types of cancer, including PCa." (PMID 35534851, 2022). "Expression levels were ranked and we found KDM4A to have the highest relative expression in MPM, in comparison to other cancer types." (PMID 34088988, 2021). "The overexpression of KDM4A promotes expression of HIFα, which increases DDIT4 levels, activating a signaling pathway that promotes cancer cell proliferation, migration and invasion." (PMID 34385569, 2021). "We determined that EPHB2 has significant interactions with several key proteins, including L1CAM, ABL2, KDM4A, BTF3, and SRC, suggesting that it may form a functional network critical to cancer progression." (PMID 41322437, 2025). "Likewise, under hypoxic conditions, KDM4A SUMOylation induces SLC7A11 upregulation, enabling cancer cells to evade ferroptosis." (PMID 41439026, 2025). "Indeed, we noted a robust correlation in the expression of KDM4A, KDM4B, KDM4C and KDM4D across all tumour samples in the TCGA pan‐cancer database." (PMID 38390756, 2024). "Moreover, KDM4A assembles into a corepressor complex with nuclear receptor corepressor (NCoR) and HDAC and silences the expression of TRAIL and DR5, which promotes cancer cell survival and desensitizes PCa cells to TRAIL." (PMID 37692513, 2023). "Accumulating evidence suggests the cancer drivers KDM4A, KDM4B, and KDM4C are overexpressed leading to the efficient growth, in a variety of human malignancies including breast, colorectal, lung, prostate, and other cancers." (PMID 36520265, 2022). "We next sought to evaluate whether KDM4B is the key member of the KDM4 family (KDM4A, KDM4B, and KDM4C) for controlling c-Myc to regulate cancer metabolism." (PMID 34335964, 2021). "Lysine demethylase 4A (KDM4A, also known as JMJD2A), a member of the histone demethylase family, is also an important target of miR-526b, whose expression is shown to be increased in various cancers." (PMID 35155211, 2021).